CD68 (CD68 molecule)
Diseases named in the same sentence as CD68 in open-access papers (continued):
Sharing a sentence is not in itself a finding about the gene and the disease.
lysosomal storage disease (1 paper, 2023). A metabolic disorder caused by mutations in proteins critical for lysosomal function, including lysosomal enzymes, lysosomal integral membrane proteins, and proteins involved in the post-translational modification and trafficking of lysosomal proteins. "Lysosomal storage disease genes include GRN, GPNMB, GAA, and CHIT1 which, according to STRING analyses, interact with CD68, CD63, and TLR3, and are known to have lysosomal membrane function." (PMID 37422510, 2023).
mastitis (1 paper, 2020). Inflammation of breast tissue during lactation or postpartum due to an obstructed duct or infection. "Among the highly connected genes in the magenta module, GCLM, PARK7, SIL1, PHB, and CD68 were potentially associated with mastitis or similar biological processes, based on the previous studies." (PMID 32754201, 2020).
melanosis (1 paper, 2020). "The dermal pigment-laden cells in Riehl’s melanosis were further evaluated for immunostaining with factor XIIIa and CD68 antibodies." (PMID 32121626, 2020). "Also, the number of CD68-positive cells was increased in the lesional skin of Riehl’s melanosis (mean ± SD = 16.66 ± 6.19) compared to perilesional normal-appearing skin (mean ± SD = 6.67 ± 4.21; p < 0.01) and healthy controls (mean ± SD = 2.25 ± 1.35; p < 0.001)." (PMID 32121626, 2020). "As CD68 is known as a macrophage marker, these observations suggest that the uptake and phagocytosis of dermal melanin might occur in the lesional skin of Riehl’s melanosis." (PMID 32121626, 2020).
memory impairment (1 paper, 2022). "As a result, 3 DEmRNAs from CCI with memory impairment model rats (ATF3, C1QC, and CD68) and 13 DEmRNAs from SNI and CCI models (ADAMTS2, BCL6B, CLCF1, RBP1, and TPBG, among others) overlapped with SNI and CCI models, respectively." (PMID 35547819, 2022).
meningeal carcinomatosis (1 paper, 2025). "We found a significant association between low expression of CD68 in the tumor nest of brain metastases and the occurrence of meningeal carcinomatosis." (PMID 40510346, 2025). "We found a significant association between low CD68 expression in the tumor nest of brain metastases and the occurrence of meningeal carcinomatosis (p = 0.016)." (PMID 40510346, 2025). "Low expression of CD68 and CD163 in brain metastases correlated with the presence of meningeal carcinomatosis." (PMID 40510346, 2025).
microcephaly (1 paper, 2019). A congenital or acquired developmental disorder in which the circumference of the head is smaller than normal for the person's age and sex. "Brain slices of a ZIKV-positive human fetus (5 months) diagnosed with microcephaly were stained for the viral protein NS1 together with the leukocyte marker CD45, the monocytic marker CD14, or the myeloid markers CD68 or CD163." (PMID 31562326, 2019).
Microscopic hematuria (1 paper, 2020). Microscopic hematuria detected by dipstick or microscopic examination of the urine. "The renal tissues of six patients with microscopic hematuria but normal histology were stained with anti-CD68 and anti-CD163." (PMID 32034190, 2020).
migraine (1 paper, 2025). "Although several markers, such as CD11β, CD68 and CD163 and iNOS have been used in migraine and neuroinflammation studies to identify functionally distinct microglial subsets, we selected Iba-1 as the sole microglial marker for this study." (PMID 41515906, 2025).
Miscarriage (1 paper, 2024). A pregnancy that ends at a stage in which the fetus is incapable of surviving on its own, defined as the spontaneous loss of a fetus before the 22th week of pregnancy. "An increase in CD68+ macrophages has been linked to miscarriage, and notably, in PCOS patients, there is an elevation of both CD68+ and CD163+ M2 macrophages." (PMID 38256276, 2024).
monocytopenia (1 paper, 2020). "Together with the clinical observation that monocytopenia patient skin has normal MAC numbers and almost no proliferative CD68+cells, yet many CD34+cells, our ex vivo-data further support that human dermal CD68+trMACs arise from an expanding pool of CD34+MAC progenitors after SP stimulation." (PMID 31971954, 2020).
Morton Neuroma (1 paper, 2025). Swelling and inflammation of the nerve between the ends of the metatarsal bones at the base of the toes. "Using immunofluorescent staining of human Morton's neuroma and control nerves, we identified persistent demyelination, an intraneural increase in CD3+ T-cell densities, and an association of CD68+ macrophages with burning pain." (PMID 39588776, 2025).
mucinous adenocarcinoma (1 paper, 2022). An invasive adenocarcinoma composed of malignant glandular cells which contain intracytoplasmic mucin. "Enteric and mixed adenocarcinoma had a higher density trend of immune cells than mucinous adenocarcinoma, especially CD4+ (p = 0.0826) and CD68+ (p = 0.1256) cells." (PMID 35158883, 2022).
mycosis fungoides (1 paper, 2025). Classical mycosis fungoides is the most common type of mycosis fungoides (MF), a form of cutaneous T-cell lymphoma, and is characterized by slow progression from patches to more infiltrated plaques and eventually to tumors. "Additionally, for mycosis fungoides (MF) and Sézary syndrome (SS), the high ratio of CD163 to CD68 in the tumor stages of MF and SS indicates M2 polarization of tumor-associated macrophages (TAMs) and correlates with tumor progression." (PMID 40426926, 2025).
myelodysplastic syndrome (1 paper, 2024). A clonal hematopoietic disorder characterized by dysplasia and ineffective hematopoiesis in one or more of the hematopoietic cell lines. "Recently, we identified polyploid giant cells expressing CD61, Syncytin-1, telomerase, Runx2, and macrophage markers (CD11b, CD68, and CD163) in the circulation of patients with myelodysplastic syndromes (MDS)." (PMID 38611120, 2024).
myelolipomas (1 paper, 2024). "The CD68 and CD117 transcripts were significantly higher (p < 0.005) in the CAH adrenal and myelolipoma compared to the normal adrenal." (PMID 38473790, 2024). "Immunohistochemistry staining revealed a higher density of inflammatory cells (CD20, CD3, CD68) in CAH compared to non-CAH myelolipomas." (PMID 38473790, 2024).
myofibroblastoma (1 paper, 2023). A benign, well circumscribed soft tissue neoplasm characterized by the presence of spindle shaped myofibroblasts and mast cells in a collagenous stroma.
myonecrosis (1 paper, 2018). "In the last experimental period examined (Day 7), the amount of myonecrosis, number of inflammatory cells, CD68+ (M1) and CD206+ (M2) macrophages as well as the expression of IL‐6, TNF‐α and TGF‐β mRNA were lower compared with previous periods (Day 2 and 4)." (PMID 30024093, 2018).
myxoid liposarcoma (1 paper, 2023). A liposarcoma characterized by the presence of round non-lipogenic primitive mesenchymal cells and small signet ring lipoblasts within a myxoid stoma with a branching vascular pattern. "Furthermore, higher levels of CD68+ TAMs were associated with a poorer OS in myxoid liposarcoma that promoted invasiveness through the heparin-binding EGF-like growth factor (HB-EGF)-EGFR-PI3K/Akt pathway." (PMID 37958467, 2023).
neck tumours (1 paper, 2020). "In this study, we apply three spatial statistics to locations of CD68+ macrophages within human head and neck tumours, and show that images grouped semi-quantitatively by a pathologist share similar statistics." (PMID 33122646, 2020).
nephritis (1 paper, 2007). Inflammation of renal tissue. "Another essential feature of the inflammatory response in HgCl2-induced nephritis is the appearance of a massive cellular infiltrate localized in the periglomerular and perivascular zone, including macrophages (CD68+) and T lymphocytes (CD3+)." (PMID 17250768, 2007).
nerve sheath tumour (1 paper, 2022). "The expression of HLA-DR and CD68 supports the induction of an APC phenotype in a nerve sheath tumour." (PMID 35323240, 2022).
neural tumours (1 paper, 2014). "However, if they do not show positive immunoreactivity or if there is difficulty in differentiation between different neural tumours we can apply other staining tests like epithelial membrane antigen (EMA), factor XIIIa, CD34 or CD68, or type IV collagen." (PMID 25478247, 2014).
neuroma (1 paper, 2006). A tumor that grows from a nerve or is composed of nerve cells and nerve fibers. "Immunostaining for CD68 showed cells with similar morphology and distribution to Cox-2 in controls, with an increase in neuromas." (PMID 16393343, 2006). "In accord with our previous report, Cox-2-IR was increased from some weeks after injury, whereas CD68-positive macrophages were increased more acutely – in this study, we have demonstrated, in addition, that the Cox-2-IR increase in macrophages persists over many years in injured human neuromas." (PMID 16393343, 2006).
nodular sclerosis Hodgkin lymphoma (1 paper, 2024). "A biopsy was performed, revealing a histological diagnosis of nodular sclerosis Hodgkin lymphoma (NSHL), stage IIA (CD30+, CD15+, CD45-, CD20-, CD42 Ro-, CD68-, EMA-, and S100-Citokeratyn-)." (PMID 39684891, 2024).
Opportunistic infection (1 paper, 2022). An infection that is caused by a pathogen that would generally not be able to cause an infection in a host with a normal immune system. "The loss of resident CD68+ macrophages increases the risk of opportunistic infections due to the inability to mount an effective adaptive immune response." (PMID 35203323, 2022). "The shift in CD68− and CD68+CD163− macrophages to a CD163 phenotype has functional implications in their ability to defend against opportunistic infections, since these cells serve as antigen-presenting cells that are required for mounting effective adaptive immune responses." (PMID 35203323, 2022).
oral epithelial dysplasia (1 paper, 2014). "The mean expression score of CD68 in normal oral mucosa was 4.99 ± 0.38, and its expression was significantly different as compared with that in oral epithelial dysplasia (5.62 ± 1.86) and OSCC (17.59 ± 1.91)." (PMID 24883329, 2014).
oral lichen planus (1 paper, 2025). Oral lichen planus is a chronic inflammatory oral condition of unknown aetiology characterized by T-cell-mediated chronic immune response and abnormal epithelial keratinization cycle. "Additionally, Oral Lichen Planus showed a significantly (p=0.029) increased CD68 and CD163 cell density and Labeling Index." (PMID 40297579, 2025).
orchitis (1 paper, 2020). Inflammation of one or both testes due to viral or bacterial infections. "Here, the number of TM subsets CD68+CD163- and (CD68+CD163+) increases progressively from the end of the immunization period to the severe orchitis stage, with minor changes in the number of resident CD163+ TM." (PMID 33101311, 2020).
oropharynx carcinomas (1 paper, 2018). A primary or metastatic malignant neoplasm that affects the oropharynx. "CD68+ macrophage numbers were significantly higher in larynx than in hypopharynx (p = 0.043) and oropharynx carcinomas (p = 0.023)." (PMID 29541395, 2018).
osteitis (1 paper, 2022). "In line with this, staining for markers on immune cells, such as CD14 and CD68, were increased in the infected groups compared to their non-infected counterparts, indicating ongoing osteitis and systemic responses of the immune system." (PMID 35268930, 2022).
osteosclerosis (1 paper, 2018). Abnormally high bone density. "There are no diagnostic criteria for this entity, and diagnosis is usually based on radiologic findings of osteosclerosis combined with histopathological evidence of foamy CD68 positive and CD1a negative histiocytic infiltration." (PMID 29875943, 2018).
ovarian endometriosis (1 paper, 2006). A non-neoplastic disorder characterized by the growth of endometrial tissue in the ovaries. "The results of statistical analysis of metallothionein (MT), RCAS1, CD68, CD56, CD16, CD25 and CD69 expression in ovarian endometriosis, scar endometriomas and secretory endometrium performed by Kruskal-Wallis analysis of variance (ANOVA) test." (PMID 16907986, 2006).
pancreatic neuroendocrine tumor (1 paper, 2016). Pancreatic endocrine tumor, also known as pancreatic neuroendocrine tumor (PNET), describes a group of endocrine tumors originating in the pancreas that are usually indolent and benign, but may have the potential to be malignant. "Presence of CD68+ macrophages within tumors have previously been linked to metastasis of mouse and human pancreatic neuroendocrine tumors, and we have shown that tumors from C5-encoding animals display CD68+ macrophages along the tumor edges." (PMID 27105526, 2016).
papilloma (1 paper, 2021). A benign epithelial neoplasm that projects above the surrounding epithelial surface and consists of villous or arborescent outgrowths of fibrovascular stroma. "Immunostaining revealed that the numbers of F4/80-, CD68- and CD206-positive cells did not obviously differ between control and Mcpip1eKO papillomas, consistent with the transcriptomic analysis results." (PMID 34903245, 2021).
paraganglioma (1 paper, 2024). A benign or malignant neoplasm arising from paraganglia located along the sympathetic or parasympathetic nerves. "The presence of CD163 and CD68 positive macrophages in pheochromocytoma and extra adrenal abdominal paragangliomas has been reported previously." (PMID 39619326, 2024).
PEComas (1 paper, 2021). "However, this also raises the differential of epithelioid PEComas, sharing the same immunoexpression pattern, except being PAX8 negative and CD68 positive." (PMID 34680535, 2021).
Peritoneal Fibrosis (1 paper, 2024). Disorder characterized by a wide range of structural changes in PERITONEUM, resulting from fibrogenic or inflammatory processes. "One study showed that overexpression of IL-10 significantly reduced infiltration of CD68+ peritoneal macrophages and thickening of the fibrous peritoneum in rats, resulting in notable relief from peritoneal fibrosis." (PMID 39749340, 2024). "There have also been reports indicating that therapeutic agents can attenuate the aggregation of CD68+ macrophages in the peritoneum, serving as a marker for mouse M1 macrophages in animal models of peritoneal fibrosis while alleviating peritoneal fibrosis." (PMID 39749340, 2024). "Administration of 3-deazaneplanocin A (3-DZNeP) in mouse models of CG- or HG-PDF-induced peritoneal fibrosis has been shown to mitigate peritoneal injury by reducing CD68+ macrophage invasion and angiogenesis through the inhibition of EZH2 methylation activity." (PMID 39749340, 2024).
phlebitis (1 paper, 2025). Inflammation of a vein. "The diagnosis is based on a combination of clinical features and histopathological findings, including the classification of lesions, the presence of polygonal histiocytes with emperipolesis, positive staining for S-100 and CD68 proteins, negative staining for CD1a, and the absence of phlebitis." (PMID 40895985, 2025).
pressure ulcers (1 paper, 2023). "We examined CD45−/CD31−/CD34+ preadipocytes and CD68+ macrophages in human granulation tissue from pressure ulcers (n=6) using immunofluorescence, immunohistochemistry, and flow cytometry." (PMID 37904253, 2023).
primary biliary cirrhosis (1 paper, 2017). "Studies on primary biliary cirrhosis have already demonstrated that infiltrating MPO+ or CD68+ inflammatory cells, mainly neutrophils or macrophages, participated in bile duct damage through nitric oxide and ROS." (PMID 28458256, 2017).
proliferative glomerulonephritis (1 paper, 2024). A constellation of renal disorders characterized by an increase number of cells in the glomerulus; these disorders generally present with nephrotic syndrome, and generally progress to end stage renal failure over a matter of weeks to years, depending on the etiology. "CD68-positive macrophages can help in objective detection of endocapillary hypercellularity in proliferative glomerulonephritis, highlighting severe and active disease and its potential as a diagnostic biomarker." (PMID 38612574, 2024).
Pruritus (1 paper, 2021). Pruritus is an itch or a sensation that makes a person want to scratch. "The number of IL-31+CD68+ cells was shown to be significantly increased in stasis dermatitis with severe pruritus compared with that without severe pruritus." (PMID 33924978, 2021).
psoriasis plaques (1 paper, 2021). "More relevant yet for the present study, CM-biosynthesized AgNPs have been shown to significantly reduce the release of NO, IL-12, and TNFα from CD68-positive macrophages in human psoriasis plaques." (PMID 35010008, 2021).
Q fever (1 paper, 2022). A bacterial infection caused by Coxiella burnetii. "Q fever AAAs and atherosclerotic AAAs contained similar numbers of CD68+ macrophages and CD3+ T cells." (PMID 35137689, 2022). "However, in Q fever AAAs, the number of CD68+CD206+ M2 macrophages was increased, while expression of GM-CSF was decreased compared to atherosclerotic AAAs." (PMID 35137689, 2022). "Percentages of CD3+ T cells, CD20+ B cells, CD1c+ cDC2, CD15+ neutrophils, and CD68+ macrophages are similar between the groups with atherosclerotic AAA and Q fever AAA." (PMID 35137689, 2022).
radiation fibrosis (1 paper, 2026). "In addition to H&E, CD68 immunohistochemistry was used to assess macrophage infiltration, and vimentin staining identified mesenchymal cells, particularly activated fibroblasts, to evaluate post-radiation fibrosis." (PMID 41552761, 2026).
relapsing polychondritis (1 paper, 2025). A rare, clinically heterogeneous, multisystemic inflammatory disease characterized by inflammation of the cartilage and proteoglycan rich structures leading to cartilage damage with joint, ocular and cardiovascular involvement. "Granulation tissue in the perichondrium among normal cartilage tissue in relapsing polychondritis has a high prevalence of CD68+ monocytes and macrophages." (PMID 40650768, 2025).
relapsing-remitting MS (1 paper, 2023). "In relapsing-remitting MS patients, immunohistochemical and quantitative PCR analyses have detected increased levels of CXCL13 in perivascular spaces and the extracellular matrix in early and highly active MS lesions characterized by high numbers of CD68+ macrophages." (PMID 38203597, 2023).
respiratory infection (1 paper, 2022). "In AGMs exposed i.t. to NiV-MY, disease begins as a respiratory infection and the virus infects airway epithelium, endothelial cells, vascular smooth muscle, and alveolar macrophages (CD68+ monocytes/macrophages) resulting in interstitial pneumonia." (PMID 35143571, 2022).
retinoblastoma (1 paper, 2025). A malignant tumor that originates in the nuclear layer of the retina. "Antigen presenting cells expressed higher levels of CD68 in retinoblastoma compared to controls." (PMID 40395327, 2025).
rheumatic diseases (1 paper, 2021). "The number of placental CD3, CD68 and CD11 cells was significantly higher in patients affected by rheumatic diseases (SSc+ORD) compared with HC." (PMID 33313931, 2021).
salivary gland cancer (1 paper, 2023). A primary or metastatic malignant neoplasm that affects the major or minor salivary glands. "A selected number of immunohistochemical markers related to TILs (CD3, CD4, CD68, and FOXP3) and TAMs (CD68 and CD163) were investigated on major salivary gland cancers." (PMID 37465638, 2023).